HNF4G (hepatocyte nuclear factor 4 gamma)
Diseases named in the same sentence as HNF4G in open-access papers (continued):
Sharing a sentence is not in itself a finding about the gene and the disease.
metabolic disorders (1 paper, 2014). "For example, TFICA associates HNF4G with metabolic disorders, which corresponds to its KEGG annotation." (PMID 24516403, 2014).
HNF4G also shares sentences with these, for which no sentence is quoted: Crohn disease (2 papers); schizophrenia (2); cervical cancer (1); Cirrhosis (1); endometrial cancer (1); Gastrointestinal hemorrhage (1); GNE myopathy (1); Insulin resistance (1); liver fibrosis (1); major depressive disorder (1); Parkinson disease (1); prostate adenocarcinoma (1).